ZSCAN30 (zinc finger and SCAN domain containing 30)
Description:
May be involved in transcriptional regulation.
Synonyms: ZNF397OS; ZNF917; ZNF-WYM
Tractability: PROTAC: UniProt records ubiquitination sites on it; ubiquitination databases record sites on it.
Gene: Protein-coding gene on chromosome 18 (35,251,058 to 35,290,245, reverse strand). Ensembl gene ENSG00000186814.
Subcellular location: Nucleus
Subcellular location (Human Protein Atlas): Nucleoplasm; Cytosol
Gene Ontology:
Molecular function: protein binding; DNA-binding transcription factor activity, RNA polymerase II-specific; RNA polymerase II cis-regulatory region sequence-specific DNA binding
Biological process: regulation of transcription by RNA polymerase II
Cellular component: nucleus; nucleoplasm
Genetic constraint (gnomAD): Loss-of-function variants: 37 observed, 46.45 expected, observed/expected ratio (o/e) 0.8, 90% interval 0.61 to 1.05. The upper end of that interval is the gene's LOEUF score, 1.05, which puts it in group 4 of 6, group 1 being the genes least tolerant of losing a copy. Missense variants: 549 observed, 613.71 expected, observed/expected ratio (o/e) 0.89, 90% interval 0.83 to 0.96. Synonymous variants: 181 observed, 214.27 expected, observed/expected ratio (o/e) 0.84, 90% interval 0.75 to 0.96.
Homologues: Orthologues: chimpanzee ZSCAN30 (99% identical), macaque ZSCAN30 (94% identical), pig ZSCAN30 (80% identical), dog ZSCAN30 (79% identical), rabbit ZSCAN30 (78% identical), rat Zscan30 (66% identical). Paralogues in human: ZNF397 (49% identical), ZSCAN12 (48% identical), ZKSCAN1 (46% identical), ZKSCAN8 (46% identical), ZKSCAN3 (44% identical), ZSCAN21 (44% identical), ZNF165 (43% identical), ZKSCAN4 (43% identical), ZSCAN26 (42% identical), ZNF394 (40% identical), ZSCAN31 (40% identical), ZSCAN23 (40% identical), and 18 more.
Diseases named in the same sentence as ZSCAN30 in open-access papers:
ZSCAN30 is named in the same sentence as 4 diseases in open-access papers, as found by Europe PMC text mining. Sharing a sentence is not in itself a finding about the gene and the disease. The quoted sentences say what the papers report.
adenosquamous carcinoma (1 paper, 2023). A carcinoma composed of malignant glandular cells and malignant squamous cells. "These included ZSCAN30 and ZIK1, whose promoters became hypermethylated only in adenosquamous carcinoma." (PMID 37742993, 2023).
ZSCAN30 also shares sentences with these, for which no sentence is quoted: colorectal cancer (1 paper); colorectal tumors (1); Obesity (1).